FGFR3 (fibroblast growth factor receptor 3)
Diseases named in the same sentence as FGFR3 in open-access papers (continued):
Sharing a sentence is not in itself a finding about the gene and the disease.
Osteochondroma (4 papers, 2015 to 2023). A common, benign cartiliginous neoplasm arising from the metaphysis of bone. "Enchondroma- and osteochondroma-like lesions were observed in several Fgfr3-deficient mouse models." (PMID 26091072, 2015). "Inducible deletion of FGFR3 in adult mice resulted in endochondromas and osteochondromas, whereas global deletion of FGFR3 and one of its ligands, FGF18, led to aberrant chondrocyte proliferation in growth plates." (PMID 34625577, 2021). "In this study, we found that postnatal chondrocyte-specific Fgfr3 deletion induced multiple chondroma-like lesions, including enchondromas and osteochondromas, adjacent to disordered growth plates." (PMID 26091072, 2015). "Typical osteochondroma- and enchondroma-like lesions were observed in the femur, tibia, and the distal radius/ulna of Fgfr3 mutant mice." (PMID 26091072, 2015). "Moreover, Judith et.al32 reported variation in expression of FGF2, FGFR2, FGFR3, PTHrP, and PTHrP‐R in osteochondroma samples from HME and non‐HME patient." (PMID 36162830, 2023). "In our study, ectopic cartilage was also observed adjacent to osteochondroma-like lesions connected to the side of growth plate cartilage in Fgfr3−/− mice; however, we were unable to determine the precise anatomical location due to structural changes caused by the presence of chondroma-like lesions." (PMID 26091072, 2015). "In conclusion, this first is the first study to demonstrate that loss of Fgfr3 leads to the downregulation of MAPK signaling and enhanced IHH expression, resulting in the formation of chondroma-like lesions, including enchondromas and osteochondromas." (PMID 26091072, 2015). "In this study, we demonstrate that conditional Fgfr3 knockout (Fgfr3 cKO) mice lacking FGFR3 in chondrocytes exhibit severe enchondroma- and osteochondroma-like lesions in the skeleton, indicating that FGFR3 is critically involved in the formation of cartilaginous tumors." (PMID 26091072, 2015).
thanatophoric dysplasia type 2 (4 papers, 2012 to 2024). Thanatophoric dysplasia characterized by a cloverleaf-like skull and straight femurs. "In mice expressing the thanatophoric dysplasia type II activating FGFR3 mutation, the defect in chondrocyte maturation and bone formation was linked to increased SOX9 protein stability." (PMID 38885336, 2024). "Molecular analysis of the gene FGFR3 on amniotic fluid—requested because the ultrasound findings of micromelia and cloverleaf skull had led to the hypothesis of thanatophoric dysplasia type II—resulted normal." (PMID 35205306, 2022). "A 12 amino acid peptide (called P3) binding with high affinity to the extracellular domain of FGFR3 has been evaluated in mice with thanatophoric dysplasia type II (TDII), a more severe form of FGFR3-related skeletal dysplasia." (PMID 28224446, 2017).
urothelial hyperplasia (4 papers, 2018 to 2023). Hyperplasia of the transitional epithelium of the urinary tract. "Mutations in chromosome 9p and fibroblast growth factor receptor 3 in normal urothelium may lead to urothelial hyperplasia or low-grade papillary urothelial carcinoma, which may also explain the difference in genetic material between CNUL and UC." (PMID 37867556, 2023). "NMIBC are reported as genomically stable tumors characterized by FGFR3 mutations or chromosomal translocations (in around 70% of low-grade tumors), which may contribute to early urothelial hyperplasia." (PMID 35897708, 2022). "The FGFR3/HRAS mutation frequently occurs during the development of urothelial hyperplasia." (PMID 29614760, 2018). "The FGFR3/RAS pathway enables tumors to progress from urothelial hyperplasia to non-invasive papillary tumors with high recurrence rates." (PMID 29614760, 2018).
uterine corpus endometrial carcinoma (4 papers, 2021 to 2022). A endometrial carcinoma (disease) that involves the body of uterus. "FGFR3 gene expression demonstrated a positive correlation between CpG single-sites promoters’ methylation in uterine corpus endometrial carcinoma and breast invasive carcinoma." (PMID 35300329, 2022). "It was found that FGFR3 expression was correlated with tumor pathological stages in several cancer types, including BLCA, KICH, KIRC, LUAD, SKCM, and uterine corpus endometrial carcinoma (UCEC) (all P < 0.05)." (PMID 34160364, 2021).
Arthritis (3 papers, 2011 to 2021). Inflammation of a joint. "FGFR3 deficiency in myeloid cells results in more severe joint destruction and synovitis in the destabilization of the medial meniscus (DMM)-induced mouse OA model and in aging mice, whilst blocking CXCR7 in FGFR3 deficiency mice relieved joint destruction of age-related/DMM-induced arthritis." (PMID 35154008, 2021). "Another study demonstrated that the absence of signaling through FGF receptor 3 (FGFR3) leads to premature cartilage degeneration and early arthritis." (PMID 23936839, 2013). "It has been also shown that the absence of signaling through Fgfr (fibroblast growth factor receptor) 3 in the joints of Fgfr3(−/−) mice produced premature cartilage degeneration and early arthritis." (PMID 22046522, 2011).
bladder (3 papers, 2011 to 2019). "Activating FGFR3-mutations targetable by FGFR-TKIs have been initially described in subsets of urogenital cancers, but more recently oncogenic mutations affecting the extracellular and transmembrane domains of FGFR3 have also been identified in a minority of pulmonary SqCCs." (PMID 31266248, 2019). "Fibroblast growth factor receptor 3–transforming acidic coiled-coil containing protein 3 (FGFR3–TACC3; FT3) is a gene fusion resulting from rearrangement of chromosome 4 that has been identified in many cancers including those of the urinary bladder." (PMID 28855393, 2017).
colorectal tumor (3 papers, 2010 to 2022). "Expression of the FGFR3-IIIc splice variant as shown by our results is generally low, but seems to be essential for the growth and migration of colorectal tumour cells." (PMID 20234367, 2010). "No information is available yet with regard to the role of the IIIc splice variant of FGFR3 in colorectal tumours." (PMID 20234367, 2010). "Expression of FGFR3 in human colorectal tumour specimens was analysed using splice variant-specific real-time reverse transcriptase PCR assays." (PMID 20234367, 2010). "Furthermore, FGFR3 and eIF4E have been found to be actively expressed in a variety of malignancies, including lung, prostate, and colorectal tumors, which cause disease." (PMID 36364261, 2022). "To investigate the role of FGFR3-IIIc in the pathogenesis of colorectal tumours, we have analysed expression of IIIb and IIIc variants in colorectal tumour tissue and examined the impact of FGFR3-IIIc signalling on growth, survival and migration of colorectal tumour cells in vitro and in vivo." (PMID 20234367, 2010). "A dominant-negative FGFR3-IIIc construct, but not the respective FGFR3-IIIb mutant, inhibits growth and survival in colorectal tumor models in vivo and in vitro and also blocks colorectal tumor cell migration." (PMID 22203889, 2012). "However, FGFR3-IIIc not only exclusively bind FGF18, but also FGFs 1, 2, 4, 8 and 9, among which FGF9 is expressed in colorectal tumour cells (data not shown)." (PMID 20234367, 2010).
ependymoma (3 papers, 2017 to 2025). A WHO grade II, slow growing tumor of children and young adults, usually located intraventricularly. "In ependymoma, moderate-to-strong FGFR3 staining was associated with tumor location, higher proliferation index, and higher grade." (PMID 28468611, 2017). "In ependymoma, moderate-to-strong expression of FGFR3 was associated with cerebral location, young patient age and poor prognosis." (PMID 28468611, 2017). "The purpose of this study was to associate FGFR1 and FGFR3 protein levels with clinical features and genetic alterations in ependymoma and pilocytic astrocytoma." (PMID 28468611, 2017). "In ependymomas, increased FGFR3 or FGFR1 expression was associated with high tumor grade, cerebral location, young patient age, and poor prognosis." (PMID 28468611, 2017). "Still, the obtained results suggest that FGFR3 immunopositivity is associated with more aggressive ependymomas." (PMID 28468611, 2017). "However, one study has shown that FGFR1 and FGFR3 IIIc splice variants are the dominant expressed isoforms in ependymoma." (PMID 37130917, 2023). "Supratentorial ependymomas in adults can mimic diffuse gliomas with FGFR3::TACC3 fusion when displaying infiltrative growth." (PMID 40417325, 2025). "In ependymoma, high FGFR1 and FGFR3 expression has been associated with high tumour grade and poor prognosis, in the absence of FGFR1 or FGFR3 mutation." (PMID 37130917, 2023). "Ependymoma cases that co-expressed moderate-to-strong levels of both FGFR3 and FGFR1 had significantly lower survival rates." (PMID 28468611, 2017). "In pilocytic astrocytoma, moderate-to-strong FGFR3 staining was mostly observed in adult patients, which is opposite to the trend in ependymoma, where moderate-to-strong FGFR3 staining was more frequent in pediatric cases." (PMID 28468611, 2017). "We used an antibody that targets amino acids 25–124 in the FGFR3 N-terminus to perform immunohistochemical (IHC) staining on 188 cases including ependymomas or pilocytic astrocytomas." (PMID 28468611, 2017). "FGFR1 and FGFR3 expression levels were detected in ependymoma and pilocytic astrocytoma tissues using immunohistochemistry." (PMID 28468611, 2017). "We used immunohistochemistry to detect FGFR1 and FGFR3 protein levels in ependymomas and pilocytic astrocytomas, and evaluated the relationship between protein expression levels, clinical features and selected genetic alterations." (PMID 28468611, 2017). "b) FGFR3 staining in pseudorosette structures in ependymoma (200× magnification)." (PMID 28468611, 2017). "This study reports variable FGFR1 and FGFR3 protein levels in ependymoma and pilocytic astrocytoma." (PMID 28468611, 2017). "Tumors with high expression of both FGFR3 and FGFR1 were associated with poor clinical prognosis in ependymoma, suggesting that aggressive supratentorial ependymomas may benefit from treatment regimens based on FGFR inhibition." (PMID 28468611, 2017). "Elevated FGFR3 immunopositivity in high-grade cerebral tumors suggests that FGFR3 immunostaining may be typical for pediatric ependymomas." (PMID 28468611, 2017). "However, the proportion of patients with moderate-to-strong FGFR3 immunostaining was higher in ependymoma when compared to the diffuse astrocytoma patient cohort (5%, or pilocytic astrocytoma (9%)." (PMID 28468611, 2017). "Further studies are warranted to evaluate whether ependymoma patients with high FGFR3 and/or FGFR1 expression could benefit from treatment with FGFR inhibitor based therapeutic approaches currently under evaluation in clinical trials." (PMID 28468611, 2017). "However, FGFR inhibition might be a suitable treatment option for ependymomas with moderate-to-strong FGFR3 or FGFR3 + FGFR1 expression, as these patients had poor prognosis and we are currently lacking efficient regimens for their treatment." (PMID 28468611, 2017). "Our results demonstrate that moderate-to-strong FGFR3 and/or FGFR1 immunostaining was detectable in most of the supratentorial ependymomas." (PMID 28468611, 2017).
ependymoma (continued). "Among ependymomas, marked (moderate-to-strong) immunostaining for FGFR1, FGFR3, or both proteins occurred more frequently in cerebral than in non-cerebral tumors (76, 32, and 19% in cerebral, cerebellar, and spinal tumors, respectively, p < 0.001, Fisher’s exact test)." (PMID 28468611, 2017). "Elevated FGFR3 and FGFR1 protein expression is common in aggressive ependymomas but likely not driven by genetic alterations." (PMID 28468611, 2017).
Hematuria (3 papers, 2020 to 2025). The presence of blood in the urine. "Ongoing studies have since led to the development of enhanced Cxbladder Detect and Triage assays, in which six DNA single nucleotide polymorphisms from FGFR3 and TERT have been integrated to further improve risk stratification in patients with hematuria." (PMID 39335740, 2024). "The sensitivity of urinary cfDNA analysis (TERT C228T, TERT C250T, and FGFR3 S249C) was 68.9% in pre-TURBT 1, and the specificity was 96.2% using the hematuria group as the control cohort." (PMID 32509577, 2020).
Hepatic fibrosis (3 papers, 2019 to 2024). The presence of excessive fibrous connective tissue in the liver. "Fgfr3, Camk4, Gpx4, Hoxd3, and Prkcb were verified to be hyper-methylated in hepatic fibrosis of mice induced by CCl4 for 8 weeks." (PMID 36594057, 2023). "In fact, while the functional role of FGFR3 and its isoforms has not yet been investigated in the context of hepatic fibrosis, its cytoprotective function in hepatocytes has been demonstrated in experimental models." (PMID 38254797, 2024).
invasive carcinoma (3 papers, 2005 to 2024). A carcinoma that is not confined to the epithelium, and has spread to the surrounding stroma. "To further analyze the role of FGFR3 in cervical tumor progression, we investigated whether FGFR3 mutations are restricted to invasive carcinoma or may occur in squamous intraepithelial lesions." (PMID 15869706, 2005). "In the cases of high grade invasive carcinoma which underwent radical cystectomy only one out of nine cases showed positivity for FGFR3." (PMID 31528172, 2019). "The FGFR3 expression was presented in 78.1% of non-invasive carcinoma." (PMID 31528172, 2019). "In order to get insight about association between S249C FGFR3 mutation and expression, we analyzed FGFR3b expression by semi-quantitative PCR in normal cervical samples and in invasive carcinomas (2 and data not shown)." (PMID 15869706, 2005).
Kyphoscoliosis (3 papers, 2015 to 2024). An abnormal curvature of the spine in both a coronal (lateral) and sagittal (back-to-front) plane. "Diastrophic dysplasia is also characterized by interpedicular narrowing of the lumbar spine but does not share other radiographic features of skeletal dysplasia with FGFR3 mutations, instead being characterized by severe epiphyseal dysplasia and marked progressive kyphoscoliosis." (PMID 32580780, 2020). "PTHrP is involved in intervertebral disc maturation and calcification, delays cellular mineralization and hypertrophy in Col IX knockout mice, and inhibits progressive kyphoscoliosis in fibroblast growth factor receptor-3 (FGFR-3) knockout mice." (PMID 38532900, 2024). "The consistency with which FGFR3−/− mice develop kyphoscoliosis during post-natal growth identify them as a valuable resource to further explore its pathogenesis and potential therapeutic options." (PMID 25852647, 2015). "The objective of this study was to use micro CT to quantify progressive kyphoscoliosis in FGFR3−/− mice and to determine if treatment with PTHrP-1-34 could inhibit curve progression." (PMID 25852647, 2015). "Like the FGFR3−/− mice, these babies show little evidence of kyphoscoliosis at birth." (PMID 25852647, 2015).
lung fibrosis (3 papers, 2017 to 2024). "miR-99a was significantly downregulated and FGFR3 was upregulated in pulmonary fibrosis." (PMID 39684337, 2024). "In addition, studies have shown that FGFR3 plays a critical role in various diseases, including pulmonary fibrosis, by regulating the MAPK signalling pathway." (PMID 39684337, 2024). "Since FGFR3 is a target of miR-99a-5p, next, we explored the role of FGFR3 in lung fibrosis." (PMID 39684337, 2024). "By constructing exosomal therapeutic cell models with different miR-99a expressions, we further demonstrated that miR-99a-5p might attenuate pulmonary fibrosis by regulating target protein FGFR3 and downstream mitogen-activated protein kinase (MAPK) signalling pathways." (PMID 39684337, 2024).
Lynch syndrome (3 papers, 2018 to 2021). An autosomal dominant hereditary neoplastic syndrome characterized by the development of colorectal carcinoma and a high risk of developing endometrial carcinoma, gastric carcinoma, ovarian carcinoma, renal pelvis carcinoma, and small intestinal carcinoma. "Patient XIII, diagnosed with Lynch syndrome (LS), only shared a Fibroblast Growth Factor Receptor (FGFR)‐3 mutation (p.R248C; c.742C>T) between both tumors." (PMID 33006377, 2021). "Whole‐genome mRNA expression profiles of 41 tumors and immunohistochemical stainings against FGFR3, KRT5, CCNB1, RB1, and CDKN2A (p16) of 37 tumors from patients with Lynch syndrome were generated." (PMID 29791078, 2018).
medulloblastoma (3 papers, 2016 to 2025). A malignant, invasive embryonal neoplasm arising from the cerebellum. "Germline variants of FGFR3 and PDGFRA were also found in medulloblastoma and gastrointestinal stromal tumors, respectively." (PMID 27701467, 2016). "Increased FGFR3 expression has been associated with treatment failure in medulloblastoma, and FGFR inhibitor treatment has demonstrated some efficacy, albeit at high doses, in some medulloblastoma cell lines." (PMID 37130917, 2023).
metastasis (3 papers, 2018 to 2021). The spread or migration of cancer cells from one part of the body (where they first appeared) to another. "The metachronous liver metastasis had the same FGFR3 mutation but lacked the PIK3CA mutation)." (PMID 33912469, 2021). "FGFR3 expression in cutaneous malignant melanoma (CMM) tissues was positively correlated with the Breslow thickness and lymph node metastasis." (PMID 31619201, 2019). "Especially FGFR1 (13% in PTvs.N and 7% in Mvs.PT to 10% in AMP), FGFR3 (7% in PTvs.N and Mvs.PT to 2% in AMP), DDR2 in lymph node metastasis (13% in Mvs.PT to 3% in AMP) and MET (7% in PTvs.N and Mvs.PT to 2% AMP, FC 2.4) seem to be similarly overexpressed." (PMID 29743718, 2018).
metastatic melanoma (3 papers, 2017 to 2020). A melanoma that has spread from its primary site to another anatomic site. "Here, we present a rare case of fibroblast growth factor receptor 3 (FGFR 3) amplified metastatic melanoma, treated rather unconventionally with FGFR 3 inhibitor erdafitinib." (PMID 33269159, 2020). "FGFR3 expression in the CMM tissues was positively correlated with lymph node metastasis, which is in agreement with the observation that FGFR3 is expressed more in metastatic melanoma cells than primary tumor cells." (PMID 31619201, 2019). "Consistently, a pronounced expression of FGFR-3 on B cells and on tumor cells could be seen in metastatic melanoma samples." (PMID 28928360, 2017).
oropharyngeal squamous cell carcinoma (3 papers, 2016 to 2022). "Fibroblast growth factor receptor 3 (FGFR3) protein was overexpressed in 48% (89/185) of oral and 59% (124/211) of oropharyngeal squamous cell carcinoma." (PMID 26711175, 2016). "In conclusion, FGFR3 protein is frequently overexpressed in oral and oropharyngeal squamous cell carcinoma." (PMID 26711175, 2016). "We have investigated FGFR3 protein expression and FGFR3 gene copy‐numbers in a single well‐documented cohort of oral and oropharyngeal squamous cell carcinoma." (PMID 26711175, 2016). "Nevertheless, mRNA levels of FGFR3 mRNA have been associated with worse DFS in oropharyngeal squamous cell carcinoma (p = 0.005) and in non-muscle-invasive bladder cancer (HR 3.78, p < 0.001)." (PMID 36142417, 2022). "In this study, we therefore investigated FGFR3 protein expression and its relation to overall survival, disease‐free survival, and regional lymph node metastases in well‐documented cohorts of oral and oropharyngeal squamous cell carcinoma (OSCC, OPSCC)." (PMID 26711175, 2016). "Therefore, it may serve as a potential therapeutic target for FGFR3‐directed therapies in oral and oropharyngeal squamous cell carcinoma." (PMID 26711175, 2016). "Fibroblast growth factor receptor 3 (FGFR3) is expressed in squamous cell carcinoma of the head and neck (SCCHN) including oropharyngeal squamous cell carcinoma (OPSCC) and is a potential therapeutic target." (PMID 33626078, 2021).